LPAR1 (lysophosphatidic acid receptor 1)
Diseases named in the same sentence as LPAR1 in open-access papers (continued):
Sharing a sentence is not in itself a finding about the gene and the disease.
cancer (78 papers, 2004 to 2025). A tumor composed of atypical neoplastic, often pleomorphic cells that invade other tissues. "LPA has been identified as a driver of cell chemotaxis and invasion, and LPAR1 expression has been associated with increased invasiveness and metastasis in other cancer identities." (PMID 36577757, 2022). "Likewise, lysophosphatidic acid receptor 1 (LPA1) is implicated in cancer cell proliferation and migration." (PMID 37749552, 2023). "GBM cancer cells show a loss of primary cilia, which leads to an increase in the distribution of LPAR1 in the plasma membrane of these cells and to an enhancement of signal transduction by this receptor as a result of a greater association of G proteins with this receptor." (PMID 36765904, 2023). "Several missense mutations of LPAR1 were also found in rat cancer tissues." (PMID 35884407, 2022). "However, to our knowledge, this is the first report of a human LPAR1 mutation having biological consequence in a human cancer." (PMID 24147068, 2013). "Parallel whole genome and transcriptome sequencing identified a cell motility driver mutation in the LPAR1 gene, and this combinatorial approach may be leveraged for precision therapy in patients with cancer by targeting expressed driver mutations." (PMID 24147068, 2013). "Besides the different expression levels and signaling transduction patterns of LPAR1 in different tumors, another significant reason for the controversy around LPAR1’s function or failed clinical trials of LPAR1 antagonists is the mutations of LPAR1 in cancer tissues." (PMID 35884407, 2022). "We have also highlighted different signaling pathways, including molecules such as STAT3, SKA1, LPAR1 and Wnt β-catenin and their involvement in cancer development through the ZFAS1/miRNAs/mRNAs axis." (PMID 40109869, 2025). "LPAR1 levels have been found to be upregulated or downregulated in different types of tumors and cancer cell lines." (PMID 40141453, 2025). "A feature space of just seven biomarkers, namely ESM1, DHRS7C, OTOP3, AADACL2, LPHN3, GABRD, and LPAR1, was sufficient to optimize a RandomForest model that achieved > 98% balanced accuracy (and performant recall) of cancer vs. normal on external validation." (PMID 39484215, 2024). "In osteosarcoma, platelet-derived LPA binds LPAR1 on the surface of cancer cells to enhance lung metastasis." (PMID 38607068, 2024). "LPAR1 and LPAR4 expression levels were highest in cancer-associated fibroblasts (CAFs), while most of the LPAR6 expression determined was in endothelial cells followed by myeloid cells and CAFs." (PMID 37372960, 2023). "LPAR1 acts in various ways throughout cancer progression and has specialized activities in distinct malignancies." (PMID 36769510, 2023). "Deletion of LPAR1 in MDA-MB-231 cells increased CXCL12-induced calcium flux and cell migration, indicating that LPA1 can inhibit CXCR4 in cancer cells expressing both receptors." (PMID 37749552, 2023). "LPAR1 and LPAR4 were highest in cancer-associated fibroblasts, while LPAR6 was highest in endothelial cells, and LPAR2 was highest in cancer epithelial cells." (PMID 37372960, 2023). "LPA signals through its six homologous receptors (LPAR1-6) that is involved in the regulation of many pathological conditions, including obesity, chronic inflammation, diabetes, neuropathy pain, and cancer." (PMID 35769713, 2022). "Different LPARs mediate radio-resistance in different cancer cells, and LPAR1 is a pronounced receptor to mediate radio-resistance because of its ability to stabilize Nrf2 via PI3K signaling." (PMID 34209775, 2021). "Agpat4-regulated production of LPA from CRC cells signals through the LPAR1/3 and p38/p65 pathways in macrophages to stimulate M1-dependent T-cell activation and cancer suppression." (PMID 32296017, 2020). "LPAR4 (P2Y9/GPR23) and LPAR5 (GPR92) in cancer cells demonstrate inhibitory effects on proliferation and migration/invasion, which is in contrast to the effects of LPAR1–3." (PMID 32887262, 2020).
cancer (continued). "In this study, based on independent datasets in the Oncomine database and TCGA datasets, we examined the LPAR1 expression level in various types of cancer." (PMID 32656075, 2020). "In cancer cells, LPAR1 contributes to DNA synthesis and cell division following lipid phosphate phosphatase-1 and LPA stimulation." (PMID 31384176, 2019). "Although accumulating evidence have revealed a role for LPAR1 in malignant tumors, few studies have focused on the role of LPAR1 in the development of ITH." (PMID 31384176, 2019). "Elevated levels of LPAR1 expression have been observed in various types of tumors and cancer cell lines, including ovarian, breast, prostate, and bladder cancer." (PMID 31323936, 2019). "Our laboratories and others reported that the LPA pathway stimulates breast and ovarian cancer metastasis, and LPAR1 antagonists significantly prevented lung, liver and bone metastasis formation." (PMID 29805748, 2018). "All current LPA blocking strategies and clinical trials related to cancer focus on its membrane receptors (LPAR1-6) and on LPAR1-3 more particularly." (PMID 29163813, 2017). "The role of LPAR1 in LPA-induced cancer invasion and oncogenesis is well established." (PMID 39187677, 2025). "Finally, accumulating evidence supports the LPAR1 participation in drug resistance, which constitutes a serious obstacle to conventional cancer therapies." (PMID 40141453, 2025). "Given the contradictory results in different cancers, our finding involving LPAR1 might provide insights for future research." (PMID 36769510, 2023). "Significantly, the action of LPA may be more pronounced in GBM cancer stem cells than non-cancer stem cells, as the former show much higher expression of LPAR1 and LPAR3." (PMID 36765904, 2023). "LPA signaling through LPAR1 contributes to the inhibition of angiogenic processes in cancer cells." (PMID 36879212, 2023). "It is also worth mentioning that in addition to LPAR1, the receptor for advanced glycation end products (RAGE) may be another important receptor causing GBM cancer cell migration." (PMID 36765904, 2023). "Indeed, the inhibition of ATX or LPAR1 is a potential therapeutic strategy in cancer and inflammatory diseases, with promising preclinical results with a good safety profile to date." (PMID 36861069, 2023). "Patients expressing high levels of CXCR4 in these cancers also had high levels of LPAR1 (right)." (PMID 37749552, 2023). "qPCR was performed to analyze the LPAR1–3 mRNA expression in different breast (cancer) cell lines." (PMID 35365723, 2022). "Consequently, there is increasing interest in developing new ATX and LPAR1 inhibitors to suppress cancer progression." (PMID 36080255, 2022). "Aberrant LPAR1 expression was evident in a variety of cancer cell lines and primary tumors." (PMID 35884407, 2022). "Cancer cells express high levels of LPAR1–3, which are GPCRs." (PMID 32887262, 2020). "This suggests an important role for the autotaxin/LPA/LPAR1 axis in cancer cell reprogramming." (PMID 31049165, 2019). "Thus, N-WASP forms a complex with Snx18 on endocytic tubules mediating LPAR1 recycling and having strong implications for chemotactic signaling and cancer cell invasion." (PMID 31668663, 2019). "In another study, using mouse models, increasing the expression of lipid phosphate phosphatase-1, which degrades extracellular LPA and decreases signaling downstream of LPAR1/2 receptors, decreases the abilities of aggressive cancer cells to produce tumors and metastases." (PMID 31049165, 2019). "LPAR1 is a potentially exciting target for cancer metastasis." (PMID 31668663, 2019). "Our newly discovered Lpar1 inhibitors intervene at a novel point in the autotaxin signaling pathway presenting an opportunity for “combinatorial” intervention in combating this aggressive cancer." (PMID 23936085, 2013).
cancer (continued). "While our primary focus was on the role of LPAR1 as a glutamate metabolic regulator in TC-anlotinib resistance, it is also possible that the MAPK pathway contributes to resistance, given its established association with chemotherapy resistance in various malignant tumors." (PMID 40512336, 2025). "LPAR1 is a type of GPCR mainly activated by binding to a ligand such as lysophosphatidic acid (LPA) in various diseases, including cancer." (PMID 40696387, 2025). "Hypoxia promotes cancer cell invasion and metastasis through signaling that is dependent upon the lysophosphatidic acid (LPA) receptor, LPA1 (LPAR1)." (PMID 38995003, 2024). "A summary of the models used for building a classifier capable of discriminating between cancer and normal samples based on the expression of seven features: ESM1, DHRS7C, OTOP3, AADACL2, LPHN3, GABRD, and LPAR1." (PMID 39484215, 2024). "Epithelial cell (primarily cancer cells) composition was significantly enriched in high-LPAR2 and -LPAR3-expressing tumors in all three cohorts (all p < 0.001) but decreased in high-LPAR1, -LPAR5, and -LPAR6-expressing tumors (all p < 0.05)." (PMID 37372960, 2023). "In contrast to LPAR1-3 and LPAR6, LPAR4 and LPAR5 negatively affected cancer cell proliferation and motility." (PMID 35769713, 2022). "In prostate PC-3 cancer cells, hyperglycemia triggers enhanced vascular endothelial growth factor-C (VEGF-C) expression via the LPAR1/3-Akt-ROS-LEDGF signaling." (PMID 34209775, 2021). "They concluded that LPAR1 expression is higher in more metastatic cell lines, that only the silencing of LPAR1 reduces LPA-induced invasion, and that LPAR1 is more highly expressed in more advanced stages of human cancer." (PMID 34440828, 2021). "Cancer stem cell (CSC)-related genes such as ALDH1A1, OCT4, and SOX2 are upregulated by activating LPAR1." (PMID 32887262, 2020). "Furthermore, in CAFs, LPA production leads to high expression of zinc finger E-box-binding homeobox 1 (Zeb1) through LPAR1 and 3/Gi/Rho signalling to promote expression of AREG, resulting in enhanced cancer invasiveness." (PMID 38607068, 2024). "Therefore, the ATX-LPA signaling pathways give a new prospect, and LPAR1 and CD97 become promising therapeutic targets in the fight against cancer metastasis." (PMID 36937386, 2023). "Cancer cell migration is an actomyosin-dependent process, consistent with the widespread effects of LPA on RHO GTPase signaling, actin and MLC2 with a major role for LPAR1." (PMID 37064875, 2023). "LPAR1–3 are phosphoproteins modulated by the natural agonist LPA, a bioactive phospholipid involved in the development but also in pathogenesis of fibrosis, inflammation, and cancer." (PMID 36577757, 2022). "Some clinical trials of LPAR1 antagonists in cancer therapy were conducted, though there were no therapeutic trials or positive results reported." (PMID 35884407, 2022). "Apart from cancer, ATX-LPAR1 combination therapy or dual inhibitors of ATX and LPAR1 could also be used to treat IPF, where this signaling pathway has major implications in driving fibrosis." (PMID 36080255, 2022). "The inhibition of ATX or LPAR1 using siRNA or small molecules disturbs the differentiation of MSC-derived fibroblasts, and it reduces the metastasis, migration, and cell proliferation of cancer cells." (PMID 34064635, 2021). "In contrast to LPAR1–3, LPAR4 and LPAR5 negatively affected cancer cell proliferation and motility." (PMID 34209775, 2021). "LPAR1 and/or LPAR3 activate Wnt/β-catenin and PI3K/AKT/mTOR pathways to induce the epithelial-to-mesenchymal transition (EMT), which is an essential step during cancer cell stemness." (PMID 32887262, 2020). "Along with the functions of MSN as a phosphate messenger between LPAR1 and GTPase, we found additional novel features of MSN as an intracellular transporter that transports STAT3 into the nuclei of TNBC cells, which is crucial for the transcription of specific genes in cancer." (PMID 40696387, 2025).
cancer (continued). "In the present study, LPAR1 KO did not affect the in vitro cell growth and initial amount of cancer cells trapped in the lung after tail vein injection, but significantly reduced the cancer engraftment." (PMID 34302117, 2021). "LPA receptor 1 (LPAR1) expressed in cancer cells is considered as an important response to LPA, and the absence of LPAR1 may affect vascular leak." (PMID 36937386, 2023).
infection (4 papers, 2020 to 2025). The state of being infected such as from the introduction of a foreign agent such as serum, vaccine, antigenic substance or organism. "LPAR1 is involved in the reorganization, migration, differentiation, and proliferation of actin cytoskeleton, as well as its response to tissue damage and infection." (PMID 38444850, 2024). "Neuronal signaling and repair genes MAGEE1 and LPAR1 also follow similar patterns of expression at each time point and are significantly elevated in BALB/c mice at each stage of infection." (PMID 33816350, 2021).
neurodevelopmental disorder (3 papers, 2021 to 2023). A behavioral and cognitive disorder with onset during the developmental period that involves impaired or aberrant development of intellectual, motor, or social functions. "For example, the nearest gene of rs140589730 is LPAR1, which was reported to participate in regulating cell proliferation, migration, survival, and apoptosis, and could cause neurodevelopmental disorders and neuropsychiatric diseases." (PMID 37236919, 2023).
neurological diseases (3 papers, 2019 to 2021). "Thus, these previous reports suggest that LPAR1–3 has a novel function in microglial activation and that its mechanism could be involved in the pathogenesis of diverse neurological diseases related to microglial activation." (PMID 34666785, 2021).
bacterial infection (1 paper, 2014). "Analyses of Lpar1−/− animals or pharmacological blockade of LPA receptors with Ki16425 revealed a major role of LPA1 in LPA-induced CYR61 and CTG expressions in bacterial infection and induction of tissue fibrosis in kidney and lungs." (PMID 24828490, 2014).
Muscular Disorders (1 paper, 2022). "From twenty genes of “Cellular Development, Cellular Movement, Skeletal and Muscular Disorders”, six DEGs in the top network related to RSK1 KO (TTLL12, ADMA22, FN1, LPAR1, MMP16, and NRN1) were highly correlated with RSK1 expression, with significant R and p values." (PMID 36684450, 2022).
LPAR1 also shares sentences with these, for which no sentence is quoted: systemic sclerosis (9 papers); fibrosis (5); brain infarction (4); metabolic disease (4); bladder cancer (3); cerebral artery (3); fibromyalgia (3); Insulin resistance (3); cervical cancer (2); experimental autoimmune encephalomyelitis (2); hypocortisolemia (2); ischemic stroke (2); neuropathic pain (2); Pain (2); retinal ischemia (2); retinopathy (2); Sepsis (2); acute lung injury (1); acute myocardial infarction (1); adenomyosis (1); adrenocortical carcinoma (1); alcoholic liver diseases (1); Allergy (1); amyotrophic lateral sclerosis (1); autoimmune disease (1); autoimmune neuropathies (1); bladder urothelial carcinoma (1); brain tumors (1); cardiovascular disease (1); celiac disease (1).
A further 48 diseases each share a sentence with LPAR1 in 1 paper.